EGFR (epidermal growth factor receptor)
Diseases named in the same sentence as EGFR in open-access papers (continued):
Sharing a sentence is not in itself a finding about the gene and the disease.
breast carcinoma (continued). "To further dissect the biological contributions of the selected PTGS2/ESR2/EGFR/JUN/and MMP2 genes in breast cancer development, we studied their correlation, as a group, to different breast cancer molecular subtypes and ER / HR status." (PMID 39707884, 2024). "When applied to transcriptome data from breast cancer patients, the eCOT identified EGFR/ERBB2 and multiple EGFR-related downstream targets as enriched in estrogen-receptor positive (ER+) breast cancers likely to recur late (≥ 5 years after initial diagnosis)." (PMID 38853832, 2024). "Having demonstrated a suppressive role for miR-770-5p in EGFR/HER2 signaling, we next explored the effect of miR-770-5p on IGF1R, the one which is another escape signaling in trastuzumab resistant breast cancer cells." (PMID 39051060, 2024). "MiR-182-5p within the extracellular vesicles of BC can specifically target and suppress the expression of CMTM7, activating the CMTM7/EGFR/AKT pathway and facilitating the progression of breast cancer." (PMID 38223763, 2024). "Studies have shown that abnormal expression of Cav-1 can enhance EGFR signaling and increase the malignant potential of MCF-7 breast cancer cells, while overexpression of Cav-1 can enhance the cell growth inhibition ability of EGFR tyrosine kinase inhibitors." (PMID 37828916, 2023). "There were 15 clusters including first-line treatment, epidermal growth factor receptor (EGFR) expression, pyrotinib-based therapy, the prognostic index, and other clusters, demonstrating the development of research focus on breast cancer brain metastasis." (PMID 37091185, 2023). "Twenty percent of breast cancers overexpress human epidermal growth factor receptor 2 (HER2), a transmembrane glycoprotein that serves as epidermal growth factor receptor (EGFR) with tyrosine-kinase activity." (PMID 36781707, 2023). "It was also found that the treatment of breast cancer and head and neck cancer cell lines with EGCG decreased the phosphorylation of the ERK, STAT3, and EGFR proteins." (PMID 37446908, 2023). "In accordance with previous reports, our results show that the simultaneous expression of EGFR and HER2 correlated with decreased survival using our breast cancer patient cohort database." (PMID 36674955, 2023). "The cooperation between EGFR and TGF-β1 signaling is also an important driver of metastasis, as shown in breast cancer cells." (PMID 37492374, 2023). "IHC has been utilized to distinguish the expression through the phenotype of breast cancer cell lines with tyrosine kinase receptors such as HER2 and the Epidermal Growth Factor receptor (EGFR)." (PMID 38137912, 2023). "YTHDF3 is another organ-specific metastasis driver that regulates the translation of key metastasis genes such as T6GALNAC5, GJA1, EGFR, and VEGFA to promote breast cancer brain metastasis." (PMID 38102722, 2023). "The amplification of the epidermal growth factor (EGF) receptor (EGFR), HER2, as well as PRLR in breast cancers, has been regarded to accelerate tumor growth by activating their downstream signaling pathways." (PMID 37415164, 2023). "The adequate task of targeting this enzyme should consider its partners such as EGFR, JNK signaling, and the molecular heterogeneity of breast cancers." (PMID 37373092, 2023). "Studies have examined the effects of varlitinib, an FDA-approved EGFR/HER2 inhibitor, on various cancers, including gastric, pancreatic, colorectal, and breast cancers." (PMID 37601068, 2023). "In human breast cancer cells, SSTR1 and SSTR5 subtypes heterodimerize with epidermal growth factor receptor and modulate the downstream MAPK pathway in an agonist-dependent manner." (PMID 38203605, 2023). "Another study performed in MDA-MB-231 breast cancer cells found that OA induced MMP-9 secretion through a PKC, Src, and EGFR-dependent pathway, whereas it induced invasion via an EGFR, Gi/Go proteins, MMPs, PKC, and Src." (PMID 37373069, 2023).
breast carcinoma (continued). "EGFR-activated AKT inhibits GSK3β activity via Ser9 phosphorylation, suppresses EGF signaling in basal-like breast cancer (BLBC) cells, reduces PD-L1 stability, and decreases cancer cell immune escape, thereby demonstrating a therapeutic benefit." (PMID 37554324, 2023). "Lapatinib is a reversible, first-generation inhibitor of EGFR type 1 (HER1) and type 2 (HER2), administered orally and approved for the treatment of breast cancer overexpressing HER2 in combination with capecitabine." (PMID 37687164, 2023). "EGFR overexpression is majorly reported in non-small cell lung cancer (NSCLC) (50–90%), followed by breast cancer (27–90%), liver cancer (68%), and glioblastoma (GBM) (40%)." (PMID 38137520, 2023). "Similar to lapatinib, gefitinib is also a tyrosine kinase inhibitor that targets EGFR and HER2 in breast cancer." (PMID 37190065, 2023). "Epidermal growth factor receptor (EGFR) is one of therapeutic targets in oncology for solid tumors originating from epithelial tissue, such as non-small-cell lung carcinoma (NSCLC) and breast cancer." (PMID 36708507, 2023). "Lapatinib, a dual EGFR and HER2neu tyrosine kinase inhibitor, is an effective agent used to treat HER2-positive breast cancer." (PMID 37576496, 2023). "Small molecule inhibitors targeting the EGFR/Eps8 complex in NSCLC and breast cancer models have shown promising results, supporting Eps8 as a potential therapeutic target in cancer." (PMID 37169593, 2023). "After prolonged treatment with HER2 antibody, trastuzumab showed upregulation of EGFR and HER3 expression in breast cancer." (PMID 37947595, 2023). "Next, we investigated the cytotoxic effect of the immunotoxin TP secreted from SMP4003 on cancer cell lines overexpressing EGFR, i.e., CT26 mouse colon carcinoma and 4T1 murine breast cancer cells." (PMID 36900277, 2023). "Both AnnexinA1 and A2 are mediators of the endocytosis of epidermal growth factor receptor (EGFR), and it is known that EGFR activity is related to breast cancer progression." (PMID 38188613, 2023). "Lapatinib, for instance, interacts to an allosteric location on EGFR and HER2 kinases and inhibits the activity of these kinases in breast cancer cells." (PMID 37711177, 2023). "To explore the correlation between EGFR and CD44, we evaluated the prognostic value of these proteins on overall survival according to mRNA expression levels in breast cancer patients." (PMID 37924112, 2023). "BG modification of MMAF has been shown to effectively induce apoptosis at nanomolar concentrations in breast cancer and human solid tumor cells when conjugated to recombinant scFv fragments targeting HER2 and EGFR." (PMID 37432459, 2023). "SERS has also been used to target HER2 on breast cancer cells and to identify other cancer markers such as PSA, BRCA1, EGFR, and others." (PMID 37232918, 2023). "PMIP was shown to reduce EGFR levels in cell culture and in the mouse mammary tumor virus-driven polyoma middle T-antigen (MMTV-PyV MT) mouse model of breast cancer." (PMID 37720348, 2023). "EGFR: The EGFR:IQGAP1 complex was identified by mass spectrometry, and later confirmed in A431 epidermoid carcinoma, breast carcinoma, and ovarian cancer cells." (PMID 37071417, 2023). "Healthy normal skin was used as a positive control for EGFR and HER2-positive breast cancer was used as a positive control for HER2." (PMID 38414930, 2023). "TFAP2C increases ERBB-related genes (EGFR, ERBB2, ERBB3), which mediate oncogenesis in ERBB2/HER2-amplified breast cancer." (PMID 37291585, 2023). "In the treatment of breast cancer, Afatinib (IC50 = 0.5 nM), a second-generation EGFR-TKI, has gained significant popularity." (PMID 38005329, 2023). "EGFR KDD was first identified in colorectal cancer and breast cancer, whereas FGFR2 KDD was first identified in gastric cancer." (PMID 36325957, 2023).
breast carcinoma (continued). "Using CRISPR/Cas9 genome-editing and single-molecule imaging techniques, we further explore the diffusion dynamics and interactions of endogenous EGFR and HER2 at the plasma membrane of two human breast cancer cell lines." (PMID 36781849, 2023). "Lapatinib and neratinib are dual-target inhibitors that stop the activity of both EGFR and HER2 and are clinically available for patients with breast cancer." (PMID 37711177, 2023). "Next, we investigated why the survival rate of breast cancer patients with the simultaneous expression of EGFR and HER2 was poorer than that of patients with EGFR expression alone." (PMID 36674955, 2023). "SDC1 is capable of modulating breast cancer stem cell phenotypes via interleukin (IL)-6/signal transducers and activators of transcription 3 (STAT3), Notch, and epidermal growth factor receptor (EGFR) signaling pathways." (PMID 36980680, 2023). "In the GENT2 and TCGA cohort analysis, EGFR mRNA expression was highest in TNBC, and breast cancer patients in the high expression group showed a notably lower probability of overall survival (p<0.001)." (PMID 37924112, 2023). "Furthermore, our recent observations on inhibition of EGF effect and dissociation of EGFR complex formation with the use of SST in breast cancer cells might serve as a possible mechanism to avert tumour growth resistance and toxicities as proposed in the use of cisplatin." (PMID 38203605, 2023). "Bioinformatic analyses of breast cancer cell line panels reveal a network linking TET1 to the hypomethylation and activation of several oncogenic pathways, such as PI3K, EGFR, and PDGF." (PMID 37296801, 2023). "If there is a widely accepted criterion for EGFR status that is similar to HER2 status, there will be a large population of patients who will benefit from GEF as their first line of therapy for breast cancer." (PMID 38090376, 2023). "Relationship between compounds, target genes, and pathways revealed that J. humile exerts its effect on breast cancer by altering, Estrogen signaling pathway, HER2, and EGFR overexpression." (PMID 37210476, 2023). "This study highlights the potential of the developed immunosensors to be used for HER-1 (EGFR) and HER-2 quantification, and therefore, for early detection of breast cancer in patients." (PMID 36979567, 2023). "Treatment with ginsenoside Rg1 has shown a notable impact on breast cancer tissues by downregulating SNAIL2 expression and significantly attenuating the expression of pivotal regulators of cell growth, including MAPK, EGFR, and TGF-β." (PMID 37818185, 2023). "In the breast cancer cell lines MDA-MB-231 and BT474, EGFR was significantly reduced 24 h after pre-miR-218 transfection (p = 0.002 and p = 0.018, respectively, white bars)." (PMID 37088795, 2023). "High expression levels of both EGFR and c-MET in a TCGA data cohort significantly correlate with unfavorable overall survival in breast cancer patients." (PMID 37924112, 2023). "EGFR and its ligand TGF-α and EGFR2 were found to be overexpressed in many breast cancer cases and are correlated with meagre prognosis, resistance, or dearth of response to treatments with hormones." (PMID 38090376, 2023). "Specifically, pachycladin A (compound 1) reduced the growth of MDA-MB-231 breast cancer cells (EC50 of 1.6 μM); this was accompanied by the inhibition of EGFR kinase activity (10 μM) as well as p-EGFR protein levels (0.5–4 μM)." (PMID 38132936, 2023). "Typical tumor antigens include CD19 and HLA class II in B cell malignancies, CD30 in Hodgkin lymphoma, epidermal growth factor receptor (EGFR) in various epithelial cancers, HER2 in breast cancer, and CD33 in acute myeloid leukemia (AML)." (PMID 37457707, 2023). "Neratinib is an irreversible EGFR, HER2/4 receptor tyrosine kinase inhibitor that was approved for use in the treatment of HER2-positive breast cancer on 17 July 2017." (PMID 36768973, 2023).
breast carcinoma (continued). "In this work, two human epidermal growth factor receptors, HER-1 and HER-2, were selected as biomarkers to enable the detection of breast cancer." (PMID 36979567, 2023). "Epidermal growth factor receptor (EGFR), a transmembrane receptor, is an attractive target for strategies of breast cancer treatment." (PMID 36794282, 2023). "In the study, it is reported that cell aggregation induces EGFR stabilization, and consequently activates the ERK survival pathway in an E-cadherin-dependent manner in Her2-positive breast cancer cells." (PMID 37866630, 2023). "First, we removed the sialic acids from Her2/neu-expressing breast carcinoma SKBR3 cells and the epidermal growth factor receptor (EGFR)-expressing epidermoid carcinoma A431 cells using a Vibrio-cholerae- derived sialidase, a sialic acid-specific glycosidase." (PMID 38138970, 2023). "EGFR, ERBB2, and ERBB4 fusions were most frequently found in glioblastoma, breast cancer and ovarian cancer, respectively." (PMID 37168365, 2023). "In our study, we revealed that proliferation, cell cycle, apoptosis, autophagy, and also the migratory potential of HIMOXOL and Br-HIMOLID in breast cancer cells are mediated by ER (MCF7) and EGFR (MDA-MB-231) receptors." (PMID 36982173, 2023). "Constitutive and induced expression of SDC2 and 4 are affected by the coordinated crosstalk between the RTK EGFR and IGFR with ERs in vitro in MCF-7 and ERβ-positive MDA-MB-231 breast cancer cells." (PMID 36980680, 2023). "This study revealed that the combination of these two substances effectively suppressed the activation of EGFR, HER-2, and c-Met receptors, indicating potential as a treatment for mitigating the invasion and migration of breast cancer cells." (PMID 38136231, 2023). "The gene enrichment analysis, functional enrichment, and pathway analysis showed that EGFR and IGF1R are genes at the initial phase of the TNBC-specific pathway, and ERBB2 and 1ESR are involved in the hormone-dependent breast cancer pathway." (PMID 37629702, 2023). "By analyzing the clinical data of surgical breast cancer patients, it was found that the simultaneous expression of EGFR and HER2 conferred a poorer prognosis compared to EGFR expression alone." (PMID 36674955, 2023). "It is well known that various signaling pathways downstream of EGFR and HER2 are responsible for tumor progression in breast cancer." (PMID 36674955, 2023). "HER2 (also known as ERBB2/neu) is a tyrosine kinase transmembrane receptor of the plHER family (EGFR/HER1, HER2, HER3, and HER4), which is amplified and/or overexpressed in various cancer types, including early-stage breast cancer." (PMID 37896184, 2023). "HER2 and epidermal growth factor receptor (EGFR) overexpressed in some breast cancer cell lines promote the growth and proliferation of breast cancer cells." (PMID 36677797, 2023). "Cells with ectopic NGFR-EGFR-FRB and NGFR-Erbb2-FKBP were selected subclonally for expression at levels comparable to endogenous EGFR and ERBB2 in breast cancer lines." (PMID 37055441, 2023). "There is a growing body of evidence linking EGFR, MAPK, and AKT signaling pathways to endocrine resistance in ER+ breast cancer." (PMID 37443749, 2023). "Although genes that are particularly specified for breast cancer, such as ESR1, PGR, HER2, EGFR, and AR are highly correlated in mRNA-protein expression, nearly 50% of gene expressions are not consistent with their protein levels both in tumors and cell lines." (PMID 37408196, 2023). "Targeting the family of HER receptors (especially HER1, EGFR, and HER2) seems like a logical approach in HER2-positive breast cancer, which makes up approximately 30% of breast cancer cases." (PMID 37759706, 2023). "For example, monoclonal antibodies or bispecific antibodies corresponding to antigens such as EGFR, VEGFR, PD-L1, TGFB1, and CTLA-4 have been used to treat tumors, such as acute lymphoma leukemia, colorectal cancer, and breast cancer." (PMID 36523779, 2022).
breast carcinoma (continued). "The basic pathways of autophagy-dependent CSC maintenance have been demonstrated to occur via the EGFR/Stat3 and TGF/Smad pathways in breast cancer stem-like cells." (PMID 35800881, 2022). "Receptor tyrosine kinases overexpressed and mutated in cancer cells have proven to be exceptionally good targets for such approaches and antibodies to the EGFR and HER2 receptors have proved very useful in the treatment of breast cancer and colon cancer." (PMID 36581692, 2022). "We therefore transfected fluorescently labelled siRNAs (commercially available, targeting 3′UTR) and tsRNAs, which were predicted to target EGFR for silencing (tsEGFR), into the BT549 breast cancer cell line." (PMID 35048990, 2022). "Zhang and colleagues focused on BT-474 and AU-565 breast cancer cells that were resistant to lapatinib, a new tyrosine kinase inhibitor of HER2/EGFR (epidermal growth factor receptor) that was used in the study to treat breast cancer that is HER2-positive." (PMID 35571115, 2022). "Epidermal growth factor receptor (EGFR/ErbB1), is onemember of this family, over expressed in 20% to 80% of breast cancers, and another member is HER2 (ErbB2/neu), is amplified and/or over expressed (i.e., HER2-positive) in 20%to 30% of breast cancers." (PMID 37654845, 2022). "A number of mAbs and Ab fragments have been developed for preclinical and clinical studies targeting anti-epidermal growth factor receptor (EGFR, known as HER1) in various malignancies, HER2 mostly in breast cancer, and HER3 in different solid tumors." (PMID 35836956, 2022). "The overexpression and/or amplification of various types of RTKs, such EGFR, HER2, IGFR in breast cancer mediates signaling cascades that stimulate cell proliferation and cell survival." (PMID 35053443, 2022). "In this study, we confirmed that the less aggressive breast cancer cell line, namely MCF-7, demonstrated a slight EGFR expression, and 7-fold IGF-IR and 2.5-fold HER2 increased levels, respectively, as compared to MDA-MB-231 cells." (PMID 35719919, 2022). "For instance, in breast cancer cells, VCAN V2 expression suppressed Snail and induced E-cadherin protein levels through inhibition of the EGFR/ERK/GSK3β axis." (PMID 36358747, 2022). "In MDA-MB-468 breast cancer cells, TRPC1 is involved in the transactivation of the epidermal growth factor receptor (EGFR) during hypoxia, leading to the increase in LC3B autophagy marker." (PMID 35806388, 2022). "It has been shown that targeting the EGFR/PCNA signalling suppresses tumour growth of triple-negative breast cancer cells and inhibit cancer growth in neuroblastoma and breast cancer mouse xenograft models." (PMID 35933325, 2022). "Lapatinib, a dual EGFR/HER2 kinase inhibitor, has been approved for oral use in patients with trastuzumab-refractory HER2-overexpressing breast cancer since 2007." (PMID 36558904, 2022). "Lapatinib is a potent double tyrosine kinase inhibitor of the epidermal growth factor receptor (EGFR) and HER-2 which inhibits the proliferation of breast cancer cells with overexpression of ErbB2 and EGFR." (PMID 36467032, 2022). "Our previous studies demonstrate that these important drug targets in breast cancer, ESR1, PGR, HER2, EGFR, and AR have a high similarity in mRNA and protein variations in both tumors and cell lines." (PMID 36360219, 2022). "As an EGFR and HER2 tyrosine kinase inhibitor, Lapatinib is approved by FDA to treat patients with HER2-positive breast cancer." (PMID 36199146, 2022). "The next generation of TKIs including afatinib, dacomitinib and neratinib are irreversible pan-HER2 inhibitors (EGFR, HER2 and HER4), with afatinib and dacomitinib approved for non-small cell lung cancer (NSCLC) while neratinib approved for breast cancers." (PMID 35295841, 2022).